G6PD (glucose-6-phosphate dehydrogenase)
Diseases named in the same sentence as G6PD in open-access papers (continued):
Sharing a sentence is not in itself a finding about the gene and the disease.
kernicterus (16 papers, 2008 to 2025). A term used pathologically to describe BILIRUBIN staining of the BASAL GANGLIA; BRAIN STEM; and CEREBELLUM and clinically to describe a syndrome associated with HYPERBILIRUBINEMIA. "G6PD mutations are important contributors to the risk for significant NHB than can even lead to kernicterus." (PMID 37508669, 2023). "Multiple reports have shown that G6PD-deficient infants are significantly predisposed to neonatal jaundice and that it is more likely to be severe enough to cause kernicterus." (PMID 35685917, 2022). "Kernicterus was highly reported in G6PD cases, birth stress on vulnerable red cells G6PD deficient increase of hemolytic crisis leading to neonatal jaundice." (PMID 33073010, 2020). "Over this time period eight infants who received phototherapy died from kernicterus and four of these were G6PD deficient." (PMID 23991145, 2013). "Mutational analysis revealed the glucose-6-phosphate dehydrogenase Mediterranean polymorphic variant, which explained the development of kernicterus after exposition of naphthalene." (PMID 18460213, 2008). "Also, despite simple and accessible treatment, even in developed countries, roughly 50% of infants with kernicterus will pass away, and 6.6% of G6PD-deficient infants will get kernicterus." (PMID 38832201, 2024). "Here, we present the first documented case of kernicterus in Panama, in a glucose-6-phosphate dehydrogenase-deficient newborn clothed in naphthalene-impregnated garments, resulting in reduced psychomotor development, neurosensory hypoacousia, absence of speech and poor reflex of the pupil to light." (PMID 18460213, 2008). "Here we presented the first documented case of kernicterus in Panama in a G6PD-deficient newborn." (PMID 18460213, 2008). "Like glucose-6-phosphate dehydrogenase (G6PD) deficient hemizygous males and homozygous females, heterozygous females could also manifest hemolytic crisis, neonatal hyperbilirubinemia or kernicterus upon exposure to oxidative stress induced by certain foods such as fava beans, drugs or infections." (PMID 30097005, 2018). "Severe NIH secondary to reduced Glucose 6-phosphate dehydrogenase (G6PD) activity is still complicated by kernicterus, which is a serious neurological disease." (PMID 38480787, 2024). "Thus, screening for G6PD can triage neonates to prevent kernicterus and long-term neurodevelopmental complications." (PMID 38832201, 2024). "Four studies reported no severe complications in G6PD-deficient new-borns with NNJ, while three works described the need for exchange transfusions, three described the occurrence of kernicterus, and two described fatal outcomes." (PMID 24568147, 2014). "Quantitative measure of G6PD activity still lacks the genotypic equivalent that is so important for defining the infants, especially heterozygous female with intermediate G6PD activities, who may be at high risk for severe NHB and even kernicterus, not less than the deficient male infants." (PMID 37508669, 2023).
leukemia (16 papers, 2011 to 2025). A malignant (clonal) hematologic disorder, involving hematopoietic stem cells and characterized by the presence of primitive or atypical myeloid or lymphoid cells in the bone marrow and the blood. "NAD-dependent deacetylase Sirtuin 2, encoded by the SIRT2 gene, promotes NADPH production and leukemia cell growth through deacetylating G6PD." (PMID 31500396, 2019). "Germline and somatic mutations can also cause severe blood disorders, such as mutations in glucose-6 phosphate dehydrogenase (G6PD) which is responsible for chronic hemolytic anemia or mutations in oncogenes or tumor suppressor genes that result in leukemia." (PMID 24705286, 2014). "In addition, recent studies demonstrated that G6PD was implicated in the development of multiple cancers, including breast cancer, liver cancer, leukaemia etc25." (PMID 27586085, 2016). "Further studies should be conducted to investigate whether G6PD deficiency can alleviate oxidative damage and hematopoietic toxicity in a G6PD mouse model and whether G6PD-deficient individuals exposed to benzene have high incidence of bone marrow depression and leukemia." (PMID 27656260, 2016). "Fermented wheat germ extract has anti-leukemia activity on the Jurkat cell line through the inhibition of glucose-6-phosphate dehydrogenase (G6PDH) and transketolase enzymes, charging to regulate carbon flux in the glycolytic and pentose pathway, respectively." (PMID 40333775, 2025). "In various types of cancers, such as breast, gastric, bladder, ovarian, prostrate, colorectal, leukemia, esophageal and lung, the activity of G6PD is increased." (PMID 37049781, 2023). "Decreasing proliferation of leukemia and other cancer cells, knockdown of G6PD significantly increased apoptosis of tumor cells which are also more susceptible to oxidative stress." (PMID 38098504, 2023). "Chemical inhibitors against SIRT2 suppress G6PD activity, leading to the reduced cell proliferation of leukemia cells." (PMID 35207558, 2022). "To this end, we examined the physiological significance of the interaction between SIRT2 and G6PD in leukaemia cells." (PMID 27586085, 2016). "Chemical inhibitors against SIRT2 effectively impaired G6PD activity and suppressed the proliferation of leukaemia cells." (PMID 27586085, 2016). "This study investigates the functional significance of PPP pathway, especially G6PD, in leukaemia development." (PMID 27586085, 2016). "We next explored the functional role of acetylation regulation of G6PD by SIRT2 in leukaemia cell proliferation." (PMID 27586085, 2016). "Together, G6PD activity is essential for both cell proliferation and colony formation of leukaemia cells, presumably through supporting de novo lipogenesis." (PMID 27586085, 2016). "In the absence of G6PD, leukaemia cells exhibited enhanced demand for exogenous lipids, indicating that G6PD-knockdown cells are possibly deficient in de novo lipogenesis." (PMID 27586085, 2016). "The observation that SIRT2-induced activation of G6PD contributes to leukaemia indicates that inhibiting SIRT2 with small molecule inhibitors may serve as a substitutive strategy to suppress G6PD." (PMID 27586085, 2016). "Alternatively, the NADPH produced by G6PD may support biosynthesis of macromolecules in leukaemia cells." (PMID 27586085, 2016). "The dependence of leukaemia cell on G6PD implies that suppression of oxidative PPP, in particular G6PD, may serve as a promising strategy to inhibit leukaemia." (PMID 27586085, 2016). "To verify this hypothesis, we established a stable human leukemia K562 cell line through G6PD gene silencing and investigated whether G6PD inhibition can enhance BQ-induced oxidative damage in K562 cells." (PMID 27656260, 2016). "In addition, activation of G6PD by SIRT2 supports the proliferation of leukaemia cell." (PMID 33630390, 2021).
leukemia (continued). "In particular, FWGE was found to inhibit Glucose-6-phosphate dehydrogenase (G6PDH), Lactate dehydrogenase (LDH) and Hexokinase (HK) activity in Jurkat T-progeny leukemia cells." (PMID 30347664, 2018). "Taken together, our study uncovers that leukaemia cells are dependent on oxidative PPP, in particular G6PD." (PMID 27586085, 2016). "Taken together, our study reveals that deacetylation of G6PD by SIRT2 sustains NADPH production and promotes leukaemia cell proliferation." (PMID 27586085, 2016). "Together, these data demonstrate that leukaemia cell proliferation is dependent on the oxidative branch of PPP, in particular G6PD, across different subtypes." (PMID 27586085, 2016). "However, the role of G6PD in metabolic reprogramming of leukaemia remains unclear." (PMID 27586085, 2016). "We demonstrated that proliferation of leukaemia cells was dependent on the oxidative branch of PPP, in particular G6PD." (PMID 27586085, 2016). "Here, we report that leukaemia cell proliferation is dependent on the oxidative branch of PPP, in particular the first and rate-limiting enzyme glucose-6-phosphate dehydrogenase (G6PD)." (PMID 27586085, 2016). "We demonstrate an approach to enhance doxorubicin cytotoxicity via the pharmacological modification of G6PD activity in both the EU1-Res and EU3-Sens leukemia cell lines." (PMID 21935349, 2011). "Activation of G6PD by SIRT2 supports the proliferation and clone formation of leukaemia cell." (PMID 33630390, 2021). "Activation of G6PD by SIRT2 supports the proliferation and clonogenic activity of leukaemia cells." (PMID 27586085, 2016). "Although G6PD serves as a potential target to suppress leukaemia, ANAD is not amenable to in vivo use because of its toxic side effects." (PMID 27586085, 2016). "Chemical inhibitors against SIRT2 suppress G6PD activity, leading to reduced cell proliferation of leukaemia cells, but not normal hematopoietic stem and progenitor cells." (PMID 27586085, 2016). "G6PD depletion did not impair redox homeostasis of leukaemia cells, as GSH/GSSG ratio and ROS level remained unchanged in G6PD-knockdown cells." (PMID 27586085, 2016). "However, we found that shRNAs or chemical inhibitors against SIRT2 downregulated G6PD activity and suppressed leukaemia cell growth irrespective of Myc expression level." (PMID 27586085, 2016).
beta thalassemia (15 papers, 2009 to 2025). Beta-thalassemia (BT) is characterized by deficiency (Beta+) or absence (Beta0) of synthesis of the beta globin chains of hemoglobin (Hb). "In a study, researcher analysed glutathione reductase, glucose-6-phosphate dehydrogenase, and glutathione peroxidase in twenty five cases of homozygous beta thalassaemia, twenty cases of heterozygous beta thalassaemia and ten controls." (PMID 22645668, 2012).
phenylketonuria (15 papers, 2008 to 2025). Phenylketonuria (PKU) is the most common inborn error of amino acid metabolism and is characterized by mild to severe mental disability in untreated patients. "It subsequently became the main laboratory in the country dedicated to newborn screening, which officially commenced in 1973 initially for PKU phenylketonuria and subsequently for G6PD glucose-6-phosphate dehydrogenase deficiency, galactosemia, and hypothyroidism." (PMID 26436103, 2015). "In our country, newborn screening has been mandatory since 2002 for congenital hypothyroidism (CH), phenylketonuria (PKU), and glucose-6-phosphate dehydrogenase (G6PD) deficiency." (PMID 40001143, 2025). "In China, screening for IEM focuses on diseases such as phenylketonuria (PKU) and congenital hypothyroidism (CH), while other regions screen for glucose-6-phosphate dehydrogenase (G6PD) deficiency, depending on the disease." (PMID 36927542, 2023). "Neonatal or newborn screening (NBS) for a series of disorders such as phenylketonuria (PKU), congenital hypothyroidism (CH), glucose-6-phosphate dehydrogenase (G6PD) deficiency and congenital adrenal hyperplasia (CAH) is widely used in most developed and some developing countries." (PMID 33073031, 2020). "The program was initiated in 1974 for Phenylketonuria (PKU) covering the Athens Metropolitan area but quickly expanded to full national coverage (over 90,000 neonates/annum) and three additional conditions (Galactosemia, congenital hypothyroidism (CH) and Deficiency of G6PD)." (PMID 33072949, 2018). "The program started in 1974 as a pilot screening for phenylketonuria (PKU) and was gradually expanded with measurement of the activity of the enzyme of glucose 6-phosphate dehydrogenase (G6PD) and the control of congenital hypothyroidism (CH) and galactosemia (TGAL)." (PMID 41164790, 2025).
pulmonary hypertension (15 papers, 2018 to 2024). Increased pressure within the pulmonary circulation due to lung or heart disorder. "G6PD-deficient mice develop spontaneous pulmonary hypertension with pulmonary artery remodeling, which is associated with increased oxidative stress." (PMID 39739870, 2024). "This “Janus-like” potential may account for the seemingly conflicting roles for G6PD mutations in pulmonary hypertension." (PMID 34068984, 2021). "Hence, reduced G6PD activity is associated with vasodilation, which may be beneficial in ameliorating pulmonary hypertension." (PMID 31500396, 2019). "In hypoxic environments, G6PD may translocate to the nucleus and regulate the expression of genes related to pulmonary hypertension pathogenesis through DNA methylation." (PMID 38589823, 2024). "Consequently, G6PD overactivation contributes to remodeling of pulmonary arterial and development of pulmonary hypertension." (PMID 31500396, 2019). "G6PD expression is enhanced in response to hypoxia (3% O2) and this results in a switch in pulmonary artery smooth muscle cell phenotype, that is, from the contractile to synthetic phenotype, thereby contributing to pulmonary arterial remodeling and pathogenesis of pulmonary hypertension." (PMID 35666067, 2022). "Interestingly, they also reported that G6PD acted to alter DNA methylation thus regulating gene expression, a novel function for G6DP contributing to the development of pulmonary hypertension." (PMID 34068984, 2021).
congenital adrenal hyperplasia (14 papers, 2016 to 2024). Congenital adrenal hyperplasia (CAH) is an inherited endocrine disorder caused by a steroidogenic enzyme deficiency that is characterized by adrenal insufficiency and variable degrees of hyper or hypo androgyny manifestations, depending of the type and the severity of the disease. "The NBS programs in Guangxi include CH, PKU, congenital adrenal hyperplasia (CAH), glucose-6-phosphate dehydrogenase (G6PD) deficiency, thalassemia, congenital deafness, and inherited metabolic diseases (IMDs)." (PMID 37252042, 2023). "In 2011, the National Neonatology Forum (NNF) recommended congenital hypothyroidism (CH), congenital adrenal hyperplasia (CAH), and glucose-6-phosphate dehydrogenase (G6PD) deficiency as the screening panel to implement for newborn screening in India." (PMID 33073021, 2020). "Our NBS panel consists of congenital hypothyroidism (CH), congenital adrenal hyperplasia (CAH) and glucose-6-phosphatedehydrogenase (G6PD) deficiency." (PMID 33072985, 2019). "Infants are also investigated for galactosemia, cystic fibrosis, biotinidase deficiency, glucose-6-phosphate dehydrogenase (G6PD) deficiency, congenital adrenal hyperplasia (CAH), and amino acid abnormalities." (PMID 38832201, 2024).
Hepatitis (14 papers, 2007 to 2026). Inflammation of the liver. "Here, we report the case of a previously healthy, non-G6PD-deficient, 27-year-old male who developed three idiosyncratic reactions: severe thrombocytopenia, aseptic meningitis, and hepatitis concurrently following TMP-SMX administration." (PMID 39221287, 2024). "In light of these findings, the present study proposes the implementation of routine G6PD level assessments and the evaluation of other relevant markers in regions where hepatitis A is endemic." (PMID 39011425, 2024). "Materials and Methods: In this prospective study, demographical information, clinical findings, and G6PD level of hepatitis A patients, who were visited at Pediatric Hematology clinic, were entered into the database." (PMID 28875002, 2017). "The diagnosis of hepatitis A infection was confirmed using an anti-HAV IgM antibody test, and G6PD enzyme activity was measured with a fluorescent spot assay." (PMID 39011425, 2024). "Interestingly, individuals with G6PD deficiency showed a higher prevalence of Hepatitis A and Hepatitis E virus infections than normal individuals, suggesting that increased oxidative stress in the absence of G6PD determined susceptibility to infection." (PMID 35071051, 2021). "As hepatitis serologies and G6PD levels are not available for this patient, it is impossible to rule out acute hepatitis as the underlying cause of the hemolysis." (PMID 18783609, 2008). "Downstream tests of rapid plasma reagin (RPR), TB interferon-gamma release assay (IGRA), hepatitis panel, Cytomegalovirus (CMV) IgG, HLA B5701, G6PD, and strongyloidiasis antibodies were negative, but hepatitis A IgG tested positive." (PMID 41181720, 2025).
parasitemia (14 papers, 2009 to 2024). "The results showed significant associations between several polymorphisms on HBB and G6PD genes, parasitemia, and white blood cells (basophils, eosinophils, and lymphocytes)." (PMID 35811813, 2022). "The result was consonant with the data of the decreasing parasitemia in G6pd-deficient mice." (PMID 34456927, 2021). "The risk of parasitemia among the G6PD normal was slightly lower than among G6PDd, but not significantly different; 3.0% vs.4.8% (OR = 0.60, 95%CI = 0.23–1.54; P = 0.29)." (PMID 25746733, 2015). "A post-hoc analysis for risk factors associated with occurrences of the composite endpoint found significant effects for G6PD-deficiency (OR 16.3, 95%CI 8.6, 31.2), treatment with CDA versus AL (OR 5.1, 95%CI 2.1, 12.4) and baseline parasitemia (OR 2.3, 95%CI 1.3, 4.3)." (PMID 19690618, 2009). "The low G6PD activity of the parasite control group as well as the primaquine treated group as found in this study is indicative of severe oxidative stress orchestrated by the pathophysiology of the parasitic infection as well as the pro-oxidant effect of the drug." (PMID 36399959, 2022). "However, these G6PD polymorphisms appear to have minor effects when compared to the strong non-genetic effects related to age, parasitemia, and Hb0." (PMID 33897764, 2021). "These study-specific effects together with the effects of parasitemia and Hb0 explained more than half of the variation observed in Hb7 and suggested that the remaining variation is not explained by the genetic variation in the G6PD locus." (PMID 33897764, 2021).